RAC1 (Rac family small GTPase 1)
Diseases named in the same sentence as RAC1 in open-access papers (continued):
Sharing a sentence is not in itself a finding about the gene and the disease.
prostate carcinoma (continued). "Rac1 hyperactivation was not related to the presence of activating Rac1 mutations and was insensitive to overexpression of a Rac-GAP or the silencing of specific Rac-GEFs expressed in prostate cancer cells." (PMID 32092966, 2020). "It has been reported that P-Rex1 is highly expressed in PC3 prostate cancer cells relative to androgen-dependent cell lines, and that silencing P-Rex1 in PC3 prostate cancer cells leads to a reduction in activated Rac1, as well as in the migratory and invasive capacity of these cells." (PMID 32092966, 2020). "Another Rac1 and Cdc42 dual-inhibitor, AZA1, identified from a screen of molecules based on modifying the structure of NSC23766, has been used in in vitro studies to target prostate cancer cells." (PMID 27104658, 2016). "This synthetic compound reduced cancer cell migration and proliferation and succeeded in increasing the survival of xenograft mouse models of prostate cancer by targeting Rac1 and Cdc42 but not RhoA." (PMID 27104658, 2016). "On the other hand, although the MEK/ERK MAPK pathway is known for its role in cell proliferation, there is little evidence that MAPK activity is increased in prostate cancer and interactions between Rac1/PAK1 and MEK/ERK is likely to be cell type-dependent." (PMID 24040362, 2013). "In contrast, AZA1 treatment caused no changes in phosphorylation of the potential Rac1 effectors ERK, JNK or p38 (data not shown), indicating that activation of these MAPK pathways is not affected by Rac1 and Cdc42 inhibition in 22Rv1 prostate cancer cells." (PMID 24040362, 2013). "Levels of Rac1 and Rac3, but not Rac2, are shown to be increased in prostate cancer patient samples compared to normal prostate." (PMID 21776386, 2011). "In the current study, we investigated the specific role of 14-3-3ζ and its dimerization in the regulation of prostate cancer (PC3) cell-matrix interactions, lamellipodia formation, motility on various extracellular matrix (ECM) proteins and transendothelial migration via activation of Rac1." (PMID 22808202, 2012). "Interestingly, the proteomics detected the atypical GEF SmgGDS, a protein reported to interact with Rac1 that indirectly contributes to Rac1 regulation; however, this atypical GEF was found to be dispensable for Rac1 hyperactivation in androgen-independent prostate cancer cells." (PMID 32092966, 2020). "Interestingly, active Rac1 levels in these cells were markedly reduced by elevations in intracellular calcium or by serum stimulation, suggesting the presence of an alternative means of Rac1 regulation in prostate cancer that does not involve previously established paradigms." (PMID 32092966, 2020). "Taken together, these results confirmed that P-Rex1 does not contribute to maintaining high Rac1-GTP levels and is dispensable for migration or invasion of androgen-independent prostate cancer cells." (PMID 32092966, 2020). "In androgen-independent prostate cancer cells, AZA1 inhibited both Rac1 and Cdc42 but not RhoA GTPase activity in a dose-dependent manner and blocked cellular migration and proliferation." (PMID 24040362, 2013). "However, in the 22Rv1 prostate cancer cells analyzed here, phosphorylation of p38 and JNK was not affected following Rac1-inhibition." (PMID 24040362, 2013). "Of interest, the tumor suppressor maspin has been reported to mediate tumor cell migration through inhibiting Rac1 and Cdc42, but not RhoA GTPase, suggesting that targeting the Rac1/Cdc42 pathways by AZA1 could counteract the activity of maspin in prostate cancer cells." (PMID 24040362, 2013). "Although the exact mechanism by which 14-3-3ζ regulates Rac1 activity in prostate cancer cells is not evident from our results, a possible mechanism would be the interaction of 14-3-3ζ with one of its guanine nucleotide exchange factors (GEF) and its delivery to Rac1 resulting in its activation." (PMID 22808202, 2012).
prostate carcinoma (continued). "In addition, ERK activity was not affected by Rac1 inhibition in lymphoma cells further suggesting that this Rac1 targeting strategy exerts its effect via modulation of the PAK1-AKT signaling pathway, but not the MAP kinases, to affect prostate cancer cell proliferation." (PMID 24040362, 2013).
colorectal cancer (71 papers, 2008 to 2025). A primary or metastatic malignant neoplasm that affects the colon or rectum. "In order to better understand the contribution of RAC1-GEFs to phenotypes associated with APC deficiency in colorectal cancer in vivo, we have undertaken comparative transcriptional profiling of APC deficient and control intestinal tissues." (PMID 33397922, 2021). "Loss of Pals1 in colorectal cancer cells results in increased Arf6 and Rac1 activity, enhanced cell migration and invasion in vitro and increased metastasis of transplanted tumor cells in mice." (PMID 33941200, 2021). "This markedly contrasts with the rare identification of Rac1 activating mutations in human colorectal cancers (0.89%)." (PMID 32178475, 2020). "High expression of Rac1 was shown to be associated with poor outcome in several human cancers, such as breast, colorectal cancers, and leukemia." (PMID 32193458, 2020). "In the presence of β-catenin staining, the scenario can be that the transcriptional effects were initiated by Rac1-dependent nuclear translocation of β-catenin followed by mutation of the Wnt ligand, and deleted in colorectal cancer (DCC)." (PMID 26307342, 2015). "In HCT116 colorectal cancer cells, which harbour constitutive activation of canonical Wnt signalling, ectopically expressed active Rac1 associated with TBEs within the promoters of Wnt-responsive genes c-Myc and Cyclin D1." (PMID 18826597, 2008). "The present study sheds some light on the mechanism underlying the cross-talk between the Tiam1/Rac1 signalling pathway and the canonical Wnt pathway in colorectal cancer cells." (PMID 18826597, 2008). "Consequently, Rac1 or its GEFs are upregulated or mutated in several types of cancer, including colorectal cancer, correlating with a poor prognosis for the patients." (PMID 36494580, 2023). "Moreover, high expression of RAC1 was shown to be associated with poor outcome in several human cancers, such as colorectal cancers, and leukaemia." (PMID 33298895, 2020). "Since Tiam1 could influence the association between β-catenin and Rac1, we were prompted to determine whether Tiam1 itself could physically interact with β-catenin in colorectal cancer cells." (PMID 18826597, 2008). "Analysing RhoA and Rac1 protein levels in Colorectal cancer (CRC) samples under mechanical strain highlights their potential as diagnostic markers." (PMID 39887960, 2025). "Increased Rac1 and Cdc42 expression and activation have been observed in human colorectal cancer samples, correlating with disease progression and poor prognosis." (PMID 40005135, 2025). "In conclusion, our study demonstrates that mechanical stimulation significantly enhances the expression of RhoA and Rac1 in colorectal cancer cells, with a clear correlation between biomarker levels and cancer stage." (PMID 39887960, 2025). "Using β2-chimaerin knockout (KO) mice crossed with the ApcMin/+ model, we demonstrate that β2-chimaerin deficiency promotes colonic polyp growth, revealing a previously unrecognized role for this Rac1-specific GAP in colorectal cancer progression." (PMID 40005135, 2025). "Tissues from patients with high stage disease, increased spread to lymph nodes, and metastases also had RAC1 overexpression that promoted EMT in colorectal cancer through the activation of STAT3." (PMID 39001533, 2024). "A previous study has also shown that mTORC1 and mTORC2 promote EMT-mediated metastasis through activation of RhoA and Rac1 in colorectal cancer." (PMID 38792011, 2024). "In particular, we demonstrated that lncH19 is required for the AS of RAC1 and the expression of RAC1B, a constitutively activated GTPase whose expression in human colorectal cancer is associated with aggressive disease and poor prognosis." (PMID 39098911, 2024).
colorectal cancer (continued). "We have recently shown that downregulation of the tight junction adapter protein Pals1 in colorectal cancer cells results in an increase of cell migration, invasion, and metastasis due to the enhanced activation of Arf6 and Rac1." (PMID 36494580, 2023). "It has been confirmed that the activation of RhoA and Rac1 enhanced the migration of colorectal cancer." (PMID 36969843, 2023). "Taken together, we identified a redundancy between SMAP1 and Pals1 in the regulation of activation of Arf6/Rac1, thereby controlling cell migration, invasion, and metastasis of colorectal cancer cells." (PMID 36494580, 2023). "Recently, we revealed a new function of the polarity regulator Pals1 in controlling cell motility of colorectal cancer cells by inhibiting Arf6, which in its turn controls Rac1-dependent lamellipodia formation and tumor cell migration/invasion." (PMID 36494580, 2023). "Zhao et al10 transfected Rac1 shRNA into Lovo colorectal cancer cells, and it showed that Rac1 gene downregulation inhibited lamellipodia formation and tumor cell migration in vitro." (PMID 37434402, 2023). "PLS1 has been reported to promote metastasis of colorectal cancer through the IQGAP1/Rac1/ERK pathway." (PMID 36895481, 2023). "Taken together, we concluded from these experiments that Pals1 functions in redundancy with SMAP1 to control the levels of active Arf6 and thus Rac1-mediated cell migration in colorectal cancer cells." (PMID 36494580, 2023). "It has been reported that Rictor/mTOR is involved in regulating EMT, motility, and metastasis of colorectal cancer via RhoA and Rac1 signaling pathways." (PMID 35982899, 2022). "Previous studies demonstrated that both Myosin X and Trio interact with DCC (deleted in colorectal cancer), a receptor of Netrin-1, and the Rac1 activation elicited by Netrin-1 is lost in the Trio-deficient cortex." (PMID 34914033, 2022). "When inhibiting mTORC1 and mTORC2, found a significantly reduced migration of colorectal cancer cells by regulation of the GTPases RhoA and Rac1." (PMID 35096817, 2021). "Studies have reported that RAC1 expression is significantly upregulated in many tumors including ovarian, breast, and colorectal cancers." (PMID 34765009, 2021). "Rac1 can participate in the regulation of intestinal stem cell proliferation and the occurrence of colorectal cancer through the activation of Wnt pathway by NF-κB or in a ROS-dependent manner." (PMID 34079763, 2021). "PLS1 drives metastasis of colorectal cancer through the IQGAP1/Rac1/ERK pathway and promotes osteoblast differentiation by regulating intracellular Ca2+." (PMID 34290731, 2021). "The Rac1-GEF FARP2 contributes to the collective invasion of colorectal cancer cells as glandular structure maintaining apico-basolateral cell polarity." (PMID 32178475, 2020). "Lastly, COL1A1 was able to activate the Wnt signalling pathway via RAC1 and promote migration in colorectal cancer." (PMID 33050615, 2020). "Our previous study showed that PKC-ζ regulates the growth of colorectal cancers cells via PKC-ζ/Rac1/Pak1/β-Catenin pathway." (PMID 30417717, 2019). "Consistently, either inhibiting mTORC1 or mTORC2 is sufficient to induce MET and enhances sensitivity to oxaliplatin-induced apoptosis via RhoA and Rac1 signaling pathways in colorectal cancer cells." (PMID 29609629, 2018). "Elevated mTOR activity regulates EMT, motility, and metastasis of colorectal cancer via RhoA and Rac1 signaling pathways." (PMID 28831205, 2017). "Here we showed that in the PTC cells RAC1b induces NF-kB activation to substantially greater levels than RAC1, whereas in colorectal cancer cells RAC1 appears to be a more effective NF-kB activator than RAC1b." (PMID 28234980, 2017). "It has been shown that mTORC1 and mTORC2 regulate motility and metastasis of colorectal cancer cells via modulating Ras homolog gene family, member A (RhoA) and Rac1 signaling." (PMID 28701918, 2017).
colorectal cancer (continued). "Using dtACPPD/shRac1 system to deplete Rac1 expression in colorectal cancer cells markedly inhibited cells migration and invasion in vitro, as well as metastasis in vivo by impairing cytoskeleton reorganization and adhesion of cell-to-extracellular matrix." (PMID 27791203, 2016). "In a colorectal carcinoma model, Rac1 deletion decreased tumor progression while over-expression of Rac1 promoted tumor formation." (PMID 27506937, 2016). "RAC1 facilitates the proliferation of intestinal stem cells, formation of intestinal adenoma, initiation of colorectal cancer and migration of cancer cells." (PMID 25371063, 2015). "This is the case of the Rac1 gene, where the constitutively active isoform Rac1b is preferentially produced in breast and colorectal cancers at various stages of neoplastic progression in response to extracellular stimuli." (PMID 23863836, 2013). "In this study, we first compared the invasiveness of a collection of colorectal cancer cell lines with their RhoA, Rac1 and Cdc42 activities." (PMID 23144867, 2012). "A marked decrease in active Cdc42 and Rac1 was observed in the most invasive colorectal cancer cell lines." (PMID 23144867, 2012). "Supporting this, both mTOR complexes mTORC1 and mTORC2 have been reported to regulate motility and metastasis of colorectal cancer via the Rac1 signaling pathway, and Rac1 has been shown to simultaneously regulate mTORC1 and mTORC2." (PMID 23285024, 2012). "Recently, we identified Rac1 GTPase as an important regulator of the canonical Wnt signalling pathway in colorectal cancer cells." (PMID 18826597, 2008). "The Rac1-specfic GEF Tiam1 is overexpressed in many colorectal cancers, and is a transcriptional target of the canonical Wnt signalling pathway." (PMID 18826597, 2008). "Taken together, our results suggest that Rac1 contributes to the transcriptional activation of endogenous Wnt target genes in colorectal cancer cells." (PMID 18826597, 2008). "To explore this possibility, we generated an HCT116 colorectal cancer cell line with stable and doxycycline-inducible expression of a constitutively active form of Rac1 (V12Rac1)." (PMID 18826597, 2008). "In this report, we aimed to elucidate the role of Rac1 in the transduction of canonical Wnt signals in colorectal cancer cells." (PMID 18826597, 2008). "We have previously shown that transient transfection of V12Rac1 activated the TOPFlash reporter in HCT116 colorectal cancer cells, whereas a dominant negative Rac1 mutant (N17Rac1) inhibited the activity of TOPFlash in these cells." (PMID 18826597, 2008). "Besides, the active form of Rac1 promotes invasion of colorectal cancer cells through activation of STAT3 pathway." (PMID 37752569, 2023). "Furthermore, the BCAR1/Rac1 axis can suppress colorectal cancer and metastasis through the Hippo, ERK, and PAK signaling pathways 38, indicating the signaling pathway is indispensable in cell signal transduction." (PMID 34326687, 2021). "Our research team found that Rac1 was significantly up-regulated in metastatic colorectal cancer tissues, and the overexpression of Rac1 can significantly promote the migration and invasion of colorectal cancer cells." (PMID 34079763, 2021). "Likewise, Rho GTPases such as RhoA, RhoC and Rac1 were found to be upregulated in colorectal carcinoma." (PMID 34151400, 2021). "Deactivation of Rac1 regulates cell migration and suppresses metastasis in colorectal cancer." (PMID 33521058, 2020). "Despite the scarce importance in IBD differentiation, the oncogenic role of miR-142-3p is well known, which promotes cellular invasion in colorectal cancer cells by activating RAC1 and the onco-suppressive activity of miR-26a, and inhibits cell aggressiveness by regulating FUT4 in CRC." (PMID 32019170, 2020).
colorectal cancer (continued). "Furthermore, Rac1 and Mapk14 connected leukocyte transendothelial migration pathway with the pathways of colorectal cancer, renal cell carcinoma, osteoclast differentiation." (PMID 32632500, 2020). "A mechanism involving RAC1 has been reported to involve the PI3K/AKT-RAC1-JNK axis in gastric adenocarcinoma, PI3K in squamous lung cancer, and the activation of STAT3 in colorectal cancer, highlighting the direct association of RAC1 activation and tumor aggressiveness." (PMID 31027363, 2019). "Consistent with our findings, a previous study found that the downstream serine/threonine kinase mTOR, which is known to be an important upstream regulator of SGK1 and plays a crucial role in promoting EMT via RhoA and Rac1 signaling in colorectal cancer (CRC)." (PMID 29609629, 2018). "Our study demonstrated that the downregulation of DMTN promoted the metastasis of colorectal cancer cells by regulating the actin cytoskeleton through RAC1 signaling activation, potentially providing a new therapeutic target to enable cancer precision medicine for CRC patients." (PMID 30514346, 2018). "Moreover, we observed inhibitory effects on migration, invasion and adhesion in HCT116 colorectal cancer cells in vitro, and our results showed that Rac1 regulated colon cancer cell matrix adhesion through the regulation of cytofilament dynamics." (PMID 27791203, 2016). "Cdc42 activity has also been implicated in the proliferation and invasion of colorectal cancer cells involving downstream PAK signaling, suggesting that Cdc42 may be a useful target for therapeutic intervention in addition to Rac1 inhibition." (PMID 24040362, 2013). "We then assessed whether invasiveness and the level of active Rho GTPases, which are key components of the invasive machinery, were correlated by comparing the level of GTP-bound Cdc42, Rac1 and RhoA in the different colorectal cancer cell lines." (PMID 23144867, 2012). "Tiam1 is a Rac1-specific GEF that is overexpressed in many colorectal cancers." (PMID 18826597, 2008). "We showed that Rac1 promotes the accumulation of β-catenin in the nucleus, and synergizes with β-catenin to augment the transcription of Wnt-responsive genes in both Wnt-active colorectal cancer cells and Wnt-inactive HEK293 cells." (PMID 18826597, 2008). "As expected, Tiam1 antibody co-precipitated Rac1 in these colorectal cancer cells." (PMID 18826597, 2008). "Of particular relevance, miR-320a was previously shown to suppress colorectal cancer progression by directly binding to the 3′-UTR of the Rac1 mRNA, leading to downregulation of Rac1 protein levels." (PMID 31515469, 2019). "In the nucleus of colorectal cancer cells, TIAM1, a RAC1-GEF, negatively regulates YAP/TAZ transcriptional activity, hence suppressing their invasiveness." (PMID 31027363, 2019). "We report that the high invasive potential of colorectal cancer cells with elevated blebbing activity correlates with both increased ROCK activation and decreased Cdc42 and Rac1 activities." (PMID 23144867, 2012). "Combined treatment with PDGF to restore Cdc42 and Rac1 function and with Y27632 to inhibit ROCK synergistically reduced the invasive potential of such colorectal cancer cells." (PMID 23144867, 2012).